RCAN2-DT (RCAN2 divergent transcript)
Gene: Long non-coding RNA gene on chromosome 6 (46,491,967 to 46,606,283, forward strand). Ensembl gene ENSG00000236466.
Gene Ontology:
Biological process: SRP-dependent cotranslational protein targeting to membrane, signal sequence recognition
Cellular component: signal recognition particle, endoplasmic reticulum targeting